LRP5 (LDL receptor related protein 5)
Diseases named in the same sentence as LRP5 in open-access papers (continued):
Sharing a sentence is not in itself a finding about the gene and the disease.
hyperlipoproteinemia (1 paper, 2011). An elevated concentration of lipoproteins. "The LRP5 polymorphism LRP5.Q89R is particularly interesting to us because it has been associated with FEVR as well as bone mass density, spinal osteoarthritis, and Type III hyperlipoproteinemia." (PMID 21528003, 2011).
intracranial hypertension (1 paper, 2023). A finding characterized by increased cerebrospinal fluid pressure within the skull. "Facial dysmorphism, signs of intracranial hypertension, and multiple cranial nerve deficits were present; to our knowledge, our case is the first report of hypo-/anosmia in LRP5 HBM, suggesting a deficit of the first cranial nerve." (PMID 37659026, 2023).
microcephaly (1 paper, 2021). A congenital or acquired developmental disorder in which the circumference of the head is smaller than normal for the person's age and sex. "A recent study on patients from 10 families of FEVR with microcephaly reported that 2 LRP5 mutations can cause FEVR with microcephaly, while AOS-related genes had not been linked to FEVR with microcephaly." (PMID 33655927, 2021).
myelocytic leukaemia (1 paper, 2014). "The LRP5 levels of pro-myelocytic leukaemia cells (HL60) were genetically modified by silencing (siRNA-LRP5) or overexpression (LRP5OE) experiments." (PMID 24266894, 2014).
myelomeningocele (1 paper, 2020). Myelomeningocele is the most severe form of spina bifida. "In mouse tooth development, the homolog Sostdc1 serves as an inhibitor of Lrp5/6-mediated Wnt signaling, but SOSTDC1 has not previously been associated with myelomeningocele." (PMID 32970752, 2020).
Nephropathy (1 paper, 2022). A nonspecific term referring to disease or damage of the kidneys. "The upregulation of LRP5 was also demonstrated in clinical nephropathy, and verified to be located in podocytes." (PMID 35710882, 2022).
parathyroid disease (1 paper, 2022). "Using NGS, we identified three pathogenic variants in two genes (CDC73 and MEN1), 10 likely pathogenic variants in six genes (CASR, CDC73, LRP5, MEN1, SDHA, and VHL), and 39 non-synonymous VUS variants that could be related to parathyroid disease." (PMID 35586626, 2022).
periapical periodontitis (1 paper, 2021). Inflammation of the periapical tissue. "We found that the A1330V variant of LRP5 was associated with periapical periodontitis." (PMID 34608236, 2021). "We hypothesized that the A1330V variant of LRP5 might be associated with apical periodontitis." (PMID 34608236, 2021).
peripheral retinal degeneration (1 paper, 2024). "The peripheral retinal degeneration was also found in both eyes of all patients with variants in LRP5." (PMID 38243264, 2024).
polycystic kidney disease (1 paper, 2025). A usually autosomal dominant and less frequently autosomal recessive genetic disorder characterized by the presence of numerous cysts in the kidneys leading to end-stage renal failure. "Some LRP5 variants also contribute to the development of adult polycystic kidney disease by reducing Wnt signaling pathway activation, as demonstrated by Luciferase assays." (PMID 40940800, 2025).
postmenopausal osteoporosis (1 paper, 2021). Metabolic disorder associated with fractures of the femoral neck, vertebrae, and distal forearm. "The past decade had witnessed frequent breaks in therapeutic development targeting LRP5 signaling, namely, the anti-DKK1 and anti-sclerostin molecules in the treatment of postmenopausal osteoporosis." (PMID 34796178, 2021).
prune belly syndrome (1 paper, 2018). "For example, Wntlss and β-catenin knockout manifesting in Prune belly syndrome and Wnt/β-catenin, Gsk-3b, Lrp5 and Lrp6 knockout causing ectopia cordis." (PMID 29483576, 2018).
pulmonary hypertension (1 paper, 2025). Increased pressure within the pulmonary circulation due to lung or heart disorder. "Furthermore, LRP5 regulates the lung microvasculature via angiopoietin-Tie 2 pathway modulation, indicating that LRP5 is a potentially effective therapeutic target in pulmonary hypertension." (PMID 40940800, 2025).
refractive error (1 paper, 2025). A defect in the focusing of light on the retina as in astigmatism, myopia, or hyperopia. "Some genes implicated in IRDs (e.g., BEST1, LRP5, MFRP) affect organogenesis, modulating ocular development in the foetal and early childhood phases, leading to early-onset myopic or hyperopic refractive errors." (PMID 41465105, 2025).
renal fibrosis (1 paper, 2020). A final common manifestation of a wide variety of chronic kidney diseases characterized by glomerulosclerosis and tubulointerstitial fibrosis. "Thus, it will be very interesting to study if human patients with loss-of-function mutations of LRP5 are less likely to develop renal fibrosis in CKD." (PMID 32345960, 2020). "The present study identified a previously undocumented pro-fibrotic function of LRP5 through direct interactions with TβRs in renal fibrosis." (PMID 32345960, 2020). "As LRP5 levels were positively correlated with those of fibrotic factors in diabetic and obstructed kidneys, we further evaluated the role of LRP5 in renal fibrosis using Lrp5−/− mice." (PMID 32345960, 2020). "In addition, we examined Lrp5’s role in renal fibrosis of OVE26 mice, a type 1 diabetic model which displays progressive albuminuria, GFR decline and renal fibrosis, recapitulating the phenotypes in diabetic patients." (PMID 32345960, 2020). "We utilized UUO to examine the effect of Lrp5 knockout on renal fibrosis." (PMID 32345960, 2020). "Our studies presented evidence suggesting that the pro-fibrotic activity of LRP5 in the kidney is through a mechanism independent of Wnt/β-catenin signaling, which may represent a new pathogenic mechanism for the progression of renal fibrosis in CKD." (PMID 32345960, 2020). "In summary, we have identified a new profibrotic role of LRP5 in driving renal fibrosis via direct interaction with TGF-β/Smad signaling, suggesting LRP5 expression as a prognostic marker for the progression of CKD." (PMID 32345960, 2020). "LRP5 levels are upregulated in CKD, correlating with renal fibrosis." (PMID 32345960, 2020).
Retinal dystrophy (1 paper, 2022). Retinal dystrophy is an abnormality of the retina associated with a hereditary process. "Ten families had variants in genes related to a syndromic disease with retinal dystrophy (COL9A1, CEP290, PCDH15, LRP5, PEX1, CFH, COL2A1 and COL11A1)." (PMID 35457050, 2022).
Sepsis (1 paper, 2021). Sepsis is defined as life-threatening organ dysfunction caused by a dysregulated host response to infection. "Among that, Lrp5, Cyp7a1, Nfkbiz, Sigmar1, Fabp7, and Hao1 have been reported in the inflammatory response and lipid metabolic process, suggesting that these genes may play an important role in modulating sepsis-induced system inflammation in WT and LBP-deficient rats after LPS injection." (PMID 35005033, 2021).
small cell lung carcinoma (1 paper, 2015). Small cell lung cancer (SCLC) is a highly aggressive malignant neoplasm, accounting for 10-15% of lung cancer cases, characterized byrapid growth, and early metastasis. "Moreover, we performed dual luciferase reporter assay and Western blot on 6 targeted genes (FZD8, ITGA10, ITPKB, LRP5, PIAS1 andRUNX1) in small cell lung carcinoma cell line NCI-H82." (PMID 26642205, 2015).
spinal diseases (1 paper, 2021). "Although LRP5‐HBM patients with overt spinal diseases were excluded from the analyses, degenerative changes may have masked age‐related spinal bone loss in individuals with LRP5‐HBM." (PMID 34532618, 2021).
tongue squamous cell carcinoma (1 paper, 2024). A squamous cell carcinoma that arises from the tongue. "In this study, the researchers investigated the role of LRP5 in tongue squamous cell carcinoma (TSCC) and its potential as a therapeutic target." (PMID 38706907, 2024). "We evaluated the effect of LRP5 knockdown on biological behaviors of tongue squamous cell carcinoma cell line CAL27 and SCC25." (PMID 38706907, 2024). "The role of LRP5, a critical receptor in the Wnt signaling pathway, remains unexplored in tongue squamous cell carcinoma (TSCC)." (PMID 38706907, 2024).
uterine corpus endometrial carcinoma (1 paper, 2025). A endometrial carcinoma (disease) that involves the body of uterus. "SNV frequency is 41 in uterine corpus endometrial carcinoma (UCEC) and 42 in SKCM for LRP5, and 44 for PPFIA1 in UCEC." (PMID 40478912, 2025).
tumor (100 papers, 2006 to 2026). "To identify the specific mediators underlying the anti-tumor activity of LRP5-overexpressing osteocyte-derived CM, we performed a mass spectrometry-based proteomic analysis." (PMID 41596426, 2026). "Although Wnt signaling is frequently associated with tumor-promoting functions, LRP5, as a co-receptor in the canonical Wnt pathway, is essential for bone protection, formation, and mechanotransduction." (PMID 41596426, 2026). "The analysis revealed that treatment with LRP5-overexpressing osteocyte-derived CM was associated with an anti-tumor immune profile in the bone marrow, including increased proportions of NK cells, B cells, and T cells." (PMID 41596426, 2026). "While Lrp5 conditional knockout mice presented severe bone loss, Lrp5-overexpressing osteocyte-derived CM rescued tumor-induced bone damage." (PMID 41750310, 2026). "In a study examining CAFs in short-term versus long-term OC survivors, the APOE(CAFs) - LRP5(tumor) interaction pattern between CAFs and tumor cells at the tumor-stroma interface was associated with short-term survival." (PMID 38164130, 2023). "By contrast, the elevated expression of Lrp5 was associated with tumorigenic behaviors of tumor cells." (PMID 34976221, 2022). "Collectively, the present study demonstrated that the Lrp5-dependent and independent loading-driven anti-tumor pathways existed, and both pathways were linked to the upregulation of tumor-suppressing chemerin and the downregulation of tumor-promoting nexin." (PMID 33450808, 2021). "In contrast, tumor DCs that are deficient in LRP5/6 or β-catenin expressed markedly higher levels of IL-12, IL-6, IL-23, and TNF-α, and lower levels of immune regulatory factors." (PMID 32132993, 2020). "The presence of LRP5 has also been linked significantly with tumor metastasis such as chondroblastic subtype of OS." (PMID 31031810, 2019). "In the tibial bone metastasis model, micro-computed tomography (micro-CT) analysis showed that LRP5-overexpressing osteocyte-derived CM increased trabecular bone volume and preserved cortical bone integrity at sites of tumor invasion, thereby attenuating bone loss." (PMID 41596426, 2026). "Furthermore, in the mouse model of tumor-driven osteolysis, the systemic administration of Lrp5 CM inhibited bone loss in the EO771 tumor-invaded proximal tibia." (PMID 34976221, 2022). "However, the tumor-induced reduction in BV/TV was greater than that caused by deletion of Lrp5 in osteocytes." (PMID 34230453, 2021). "In conclusion, our study demonstrates that as the matrix-laden and most abundant cells in bone, osteocytes—and their CM—can inhibit tumor progression and bone loss and that this capability is enhanced by activating Wnt signaling via Lrp5 and β-catenin overexpression." (PMID 34230453, 2021). "Furthermore, tumor DCs that are deficient in LRP5/6 or β-catenin express markedly lower levels of IL-10 and are more potent in cross-priming CD8+ T cells." (PMID 32132993, 2020). "Furthermore, blocking Wnt interaction with LRP5/6 and Fzd using small molecule inhibitors in tumor-bearing mice showed increased capture of tumor-associated antigen by DCs." (PMID 27833613, 2016). "Besides genes with metabolic functions, these include cell type-selective genes associated with immune regulation and tumor progression, e.g., LRP5, CD300A, MAP3K8 and ANGPTL4." (PMID 25968567, 2015). "Previous studies have shown that upregulation of low-density lipoprotein receptor-related protein 5 (LRP5) in osteocytes exerts inhibitory effects on tumor cells." (PMID 41596426, 2026). "Knockdown of LIMA1 using shRNA reversed the anti-tumor effects of LRP5-overexpressing osteocyte-derived CM, confirming LIMA1’s role as a key downstream effector molecule of the LRP5/Wnt pathway." (PMID 41596426, 2026).
tumor (continued). "Collectively, these findings demonstrate that LRP5-overexpressing osteocyte-derived CM exerts its anti-tumor effects on EO771 cells primarily through the LIMA1–MYO5B signaling axis, with LIMA1 acting functionally via MYO5B." (PMID 41596426, 2026). "This study elucidates how the LRP5/Wnt signaling axis mediates anti-tumor effects by regulating the secretion of LIMA1 from osteocytes." (PMID 41596426, 2026). "In breast cancer, loss of Akkermansia muciniphila-derived butyrate, a histone deacetylase (HDAC) inhibitor that suppresses Wnt/β-catenin signaling via LRP5 destabilization, promotes tumor stemness and accelerates tumor progression." (PMID 41362728, 2026). "Collectively, our findings define the LRP5/LIMA1/MYO5B axis as a novel signaling pathway that repurposes a canonical Wnt signaling component for tumor suppression." (PMID 41596426, 2026). "The molecular mechanisms by which DKK1 promotes tumor progression, metastasis, and immune evasion are driven by its interaction with cell-surface receptors, specifically LRP5/6 and CKAP4." (PMID 42123366, 2026). "Histological analysis of H&E-stained tibial sections further revealed that the tumor infiltration area was significantly smaller in mice treated with LRP5-overexpressing osteocyte-derived CM than in the control group." (PMID 41596426, 2026). "Consistently, treatment of 4T1.2 and MCF-7 cells with LRP5-overexpressing osteocyte-derived CM also produced robust anti-tumor effects, further validating our previous observations." (PMID 41596426, 2026). "Together, these findings suggest that LIMA1 in LRP5-overexpressing osteocyte-derived CM promotes an anti-tumor immune phenotype by driving M1 macrophage polarization in an LIMA1-dependent manner." (PMID 41596426, 2026). "Together, these results confirm that LIMA1 is a major contributor to the anti-tumor activity of CM derived from LRP5-overexpressing osteocytes." (PMID 41596426, 2026). "Beyond characterizing the inhibition of tumor progression, we also examined the regulatory effects of LRP5-overexpressing osteocyte-derived CM on RANKL-induced osteoclast differentiation and immune cell activation." (PMID 41596426, 2026). "This causes LRP5 downregulation and suppression of WNT/β-catenin activity, attenuating cancer stemness and tumor growth." (PMID 40038255, 2025). "Anti-LRP5 polyclonal antibodies are widely used as antitumor drugs in breast carcinoma, reducing tumor cell viability and enhancing apoptosis by reducing β-catenin activity." (PMID 40940800, 2025). "We identify rtSPIRE1 as a novel binding partner of LRP5, providing new insights into LRP5-mediated signaling in tumor progression." (PMID 40713830, 2025). "Secreted WNT5A was suggested to interact with a wide range of tumor cell-expressing receptors, such as LRP5, LRP6, FZD5, and FZD6." (PMID 40524253, 2025). "The lung metastasis nude mice model and subcutaneous tumor model were established, the proliferation and invasion ability of tumor cells in vivo was evaluated after LRP5 knockdown." (PMID 38706907, 2024). "The first type is to knockdown the expression of LRP5 through siRNA or shRNA lentivirus, and it is found that knockdown the expression of LRP5 can inhibit the growth of tumor cells." (PMID 38706907, 2024). "Short term survival samples are enriched for SMA,VIM, and PDGFR CAFs, and show more crosstalk between CAF APOE and tumor LRP5 at the tumor-stroma interface, supported by staining and in vitro experiments." (PMID 38525245, 2024). "RNF43 is a tumor suppressor negatively regulating the Wnt signaling pathway by degrading the Wnt Frizzled-LRP5/6 complex." (PMID 38725616, 2024). "Compared to those of control xenografts, LRP5 knockdown accelerated the tumor growth in nude mice by weight over a period of 30 days in the subcutaneous tumor model." (PMID 38706907, 2024). "Subsequently, LRP5/6 were found to play a crucial role in Wnt1-dependent tumor development in transgenic mouse models 7-9." (PMID 38706907, 2024).